DUX4 (double homeobox 4)
Diseases named in the same sentence as DUX4 in open-access papers (continued):
Sharing a sentence is not in itself a finding about the gene and the disease.
facioscapulohumeral muscular dystrophy (continued). "Diminished SMCHD1 function in muscle fibers causes Facioscapulohumeral Muscular Dystrophy (FSHD2) through derepression of the D4Z4 chromatin domain, an event which permits the aberrant expression of the disease-causing gene DUX4." (PMID 38994563, 2024). "A human genetic disease, facioscapulohumeral muscular dystrophy (FSHD), features acute inhibition of NMD upon expression of the disease-causing transcription factor, DUX4." (PMID 37314931, 2023). "Facioscapulohumeral muscular dystrophy (FSHD), one of the most common muscular dystrophies, is caused by an abnormal expression of the DUX4 gene in skeletal muscles, resulting in muscle weakness." (PMID 37760780, 2023). "Human mesenchymal stromal cells (hMSC) and mesangioblasts of facioscapulohumeral muscular dystrophy (FSHD) are the other somatic/potent cells revealed to express DUX4." (PMID 34854471, 2022). "Facioscapulohumeral muscular dystrophy (FSHD), a common form of muscular dystrophy, is caused by a genetic mutation that alters DUX4 gene expression." (PMID 35451178, 2022). "Silencing the expression of the double homeobox 4 (DUX4) gene offers great potential for the treatment of facioscapulohumeral muscular dystrophy (FSHD)." (PMID 35884928, 2022). "The inhibition of aberrant DUX4 expression in the adult muscular dystrophy, facioscapulohumeral muscular dystrophy (FSHD) has also been investigated as a potential therapeutic strategy." (PMID 35067193, 2022). "Facioscapulohumeral muscular dystrophy results from the inappropriate expression of a gene called Double Homeobox 4 (DUX4)." (PMID 34502190, 2021). "DUX (DUX4 in human) was first identified to be aberrantly expressed in facioscapulohumeral muscular dystrophy (FSHD) in humans, a disorder that is characterized by an unusually high transcriptional output of ERVs." (PMID 34691189, 2021). "In humans, the subtelomeres are mosaics of ~50 types of common segments containing various ORFs, such as those for the DUX4 gene, which is related to facioscapulohumeral muscular dystrophy, and for the olfactory receptor family genes." (PMID 33504776, 2021). "While DUX4 is epigenetically silenced in most somatic tissues of healthy humans, its aberrant reactivation is associated with several diseases, including cancer, viral infection and facioscapulohumeral muscular dystrophy (FSHD)." (PMID 34943834, 2021). "Another example is facioscapulohumeral muscular dystrophy (FSHMD), associated with aberrant expression of the full-length isoform of DUX4 (DUX4-FL)." (PMID 32899400, 2020). "DUX4 is normally expressed in germ cells and early embryo, and silenced in adult muscle cells where its pathological reactivation leads to Facioscapulohumeral muscular dystrophy." (PMID 32647247, 2020). "In another example, overexpression of the double homeobox transcription factor DUX4, observed muscular dystrophy, facioscapulohumeral muscular dystrophy (FSHD), leads to activation of UPF1 proteolytic degradation and, therefore, NMD inhibition." (PMID 32213869, 2020). "Facioscapulohumeral muscular dystrophy (FSHD) is a prevalent, incurable myopathy, linked to epigenetic derepression of D4Z4 repeats on chromosome 4q, leading to ectopic DUX4 expression." (PMID 30462217, 2019). "Facioscapulohumeral muscular dystrophy (FSHD) is caused by the inappropriate expression of an early embryonic transcriptional activator, DUX4, in adult muscle, leading to cell death." (PMID 30644821, 2019). "The Double homeobox 4 (DUX4) gene is an important regulator of early human development and its aberrant expression is causal for facioscapulohumeral muscular dystrophy (FSHD)." (PMID 29415061, 2018). "Recent studies have described the functions of Pax7 in muscle diseases: PAX7-target genes are globally repressed by the DUX4 transcription factor, which is ectopically expressed in muscles of facioscapulohumeral muscular dystrophy (FSHD) patients." (PMID 30139390, 2018).
facioscapulohumeral muscular dystrophy (continued). "Facioscapulohumeral muscular dystrophy (FSHD) is a prevalent, incurable myopathy, linked to hypomethylation of D4Z4 repeats on chromosome 4q causing expression of the DUX4 transcription factor." (PMID 29255294, 2017). "Facioscapulohumeral muscular dystrophy (FSHD) is most commonly inherited in an autosomal dominant pattern and caused by the abnormal expression of DUX4 in skeletal muscle." (PMID 28637492, 2017). "Facioscapulohumeral muscular dystrophy (FSHD) involves sporadic expression of DUX4, which inhibits myogenesis and is pro-apoptotic." (PMID 27841748, 2016). "DUX4 is a pro-apoptotic protein in the D4Z4 locus, made up of tandem copies of a 3.3-kb repeat, which has been linked to facioscapulohumeral muscular dystrophy." (PMID 26335491, 2015). "Facioscapulohumeral muscular dystrophy (FSHD) is a muscular dystrophy caused byinefficient epigenetic repression of the D4Z4 macrosatellite array and somaticexpression of the DUX4 retrogene." (PMID 25564732, 2015). "Facioscapulohumeral muscular dystrophy (FSHD) is caused by epigenetic alterations at the D4Z4 macrosatellite repeat locus on chromosome 4, resulting in inappropriate expression of the DUX4 protein." (PMID 24484587, 2014). "Our particular interest in the DUX family stems from the involvement of one member (DUX4) in the molecular pathogenesis of facioscapulohumeral muscular dystrophy (FSHD)." (PMID 21110847, 2010). "Similarly, DUX4 derepression in muscle cells causes the human disease facioscapulohumeral muscular dystrophy (FSHD), characterized by up-regulation of DUX4 target genes, dsRNAs, TEs, and apoptosis." (PMID 35273077, 2022). "As models of disease, iMyoblasts from individuals with Facioscapulohumeral Muscular Dystrophy revealed a previously unknown epigenetic regulatory mechanism controlling developmental expression of the pathological DUX4 gene." (PMID 35076017, 2022). "DUX4 aberrant reactivation or gene rearrangements are associated with several diseases, including infection by viruses of the Herpesviridae family, acute lymphoblastic leukemia, undifferentiated round cell sarcoma, several neoplasms and facioscapulohumeral muscular dystrophy (FSHD)." (PMID 34943834, 2021). "A recent study could show that MRI characteristics, especially T2‐weighted sequence, muscle pathology, and expression of DUX4 target genes in a patient sample of facioscapulohumeral muscular dystrophy." (PMID 32860496, 2020). "Facioscapulohumeral muscular dystrophy is a slowly progressive but devastating myopathy caused by loss of repression of the transcription factor DUX4; however, DUX4 expression is very low, and protein has not been detected directly in patient biopsies." (PMID 28916757, 2017). "Facioscapulohumeral muscular dystrophy is a severe myopathy that is caused by abnormal activation of DUX4, and for which a suitable mouse model does not exist." (PMID 28916757, 2017). "DUX4 is typically a repressed transcription factor, but its aberrant activation in Facioscapulohumeral Muscular Dystrophy (FSHD) leads to cell death by disrupting muscle homeostasis." (PMID 39796228, 2025). "Aberrant expression of the double homeobox 4 (DUX4) gene in skeletal muscle predominantly drives the pathogenesis of facioscapulohumeral muscular dystrophy (FSHD)." (PMID 39000102, 2024). "Aberrant expression of the transcription factor DUX4 from D4Z4 macrosatellite repeats on chromosome 4q35, and its transcriptome, associate with pathogenesis in facioscapulohumeral muscular dystrophy (FSHD)." (PMID 36158201, 2022). "Aberrant expression of the double homeobox 4 (DUX4) gene in skeletal muscle causes muscle deterioration and weakness in Facioscapulohumeral muscular dystrophy (FSHD)." (PMID 33987655, 2021). "DUX4 is known for its involvment in early embryogenesis and facioscapulohumeral muscular dystrophy (FSHD)." (PMID 34642317, 2021).
facioscapulohumeral muscular dystrophy (continued). "Facioscapulohumeral muscular dystrophy (FSHD) is caused by epigenetic dysregulation of the 4q35 D4Z4 macrosatellite repeat, which leads to aberrant myogenic expression of the Double homeobox 4 (DUX4) gene." (PMID 29415061, 2018). "Here we show that the endogenous facioscapulohumeral muscular dystrophy-specific DUX4 polyadenylation signal is surprisingly inefficient, and use this finding to develop an facioscapulohumeral muscular dystrophy mouse model with muscle-specific doxycycline-regulated DUX4 expression." (PMID 28916757, 2017). "Facioscapulohumeral muscular dystrophy (FSHD) is associated with the deletion of the D4Z4 macrosatellite repeats on chromosome 4q35, which increases expression of double homeobox 4 (DUX4)." (PMID 26798425, 2016). "Misexpression of the double homeodomain transcription factor DUX4 results in facioscapulohumeral muscular dystrophy (FSHD)." (PMID 26823969, 2016). "Facioscapulohumeral muscular dystrophy (FSHD) is caused by contractions of D4Z4 repeats at 4q35.2 thought to induce misregulation of nearby genes, one of which, DUX4, is actually localized within each repeat." (PMID 19756142, 2009). "Facioscapulohumeral muscular dystrophy (FSHD) is genetically associated with reduction of the D4Z4 macrosatellite array at 4q35 on a permissive 4qA haplotype, a configuration that enables the stable expression of the DUX4 transcription factor." (PMID 41535478, 2026). "The double homeobox 4 gene (DUX4) and its centromeric paralogue, DUX4C, reside in the subtelomeric region of chromosome 4 and have been implicated in facioscapulohumeral muscular dystrophy (FSHD) and cancers." (PMID 41540238, 2026). "DUX4 is a transcription factor that plays an important role in early embryonic development and pathological conditions, particularly facioscapulohumeral muscular dystrophy (FSHD) and several types of cancer." (PMID 40427614, 2025). "Dr. Darko Bosnakovski (University of Minnesota, Minnesota, United States) demonstrated the metalloproteases (MMPs) were the culprit in Facioscapulohumeral muscular dystrophy (FSHD), by using a Dux4 overexpression mouse model to mimic the FSHD." (PMID 41245273, 2025). "In cells derived from facioscapulohumeral muscular dystrophy (FSHD) patients, CRISPR can be used to ablate expression of the toxic DUX4 protein by deleting specific genomic sequences or suppressing DUX4-encoding transcripts." (PMID 38607035, 2024). "Facioscapulohumeral muscular dystrophy (FSHD) is the third most common hereditary muscular dystrophy, caused by the contraction of the D4Z4 repeats on the permissive 4qA haplotype on chromosome 4, resulting in the faulty expression of the DUX4 gene." (PMID 38136988, 2023). "Further studies on the function of DUX4 in hematopoietic cells can shed light on DUX4-related pathways, and contribute to the treatment of DUX4-related diseases such as B-ALL, other cancers, and facioscapulohumeral muscular dystrophy." (PMID 34854471, 2022). "In this review CRS Banerji and PS Zammit discuss the relationship between transcription factors DUX4 and PAX7 in the pathology of facioscapulohumeral muscular dystrophy." (PMID 34151531, 2021). "In human muscle cells, aberrantly expressed DUX4 binds to and induces HERVL expression, which serves as alternative promoters to alter the transcription network in facioscapulohumeral muscular dystrophy." (PMID 33727936, 2021). "For example, expression of DUX4, an activator of the zygotic genome in humans, in muscle cells leads to Facioscapulohumeral muscular dystrophy (FSHD), and OCT4 and Nanog are overexpressed in undifferentiated tumors and their expression is associated with poor clinical outcomes." (PMID 34887421, 2021).
facioscapulohumeral muscular dystrophy (continued). "It is known that contraction of these D4Z4 macro-satellite sequences is associated with decreased cytosine methylation and an open chromatin structure, leading to infrequent sporadic expression of the DUX4 gene in the skeletal muscle that results in facioscapulohumeral muscular dystrophy (FSHD)." (PMID 32883366, 2020). "Facioscapulohumeral muscular dystrophy (FSHD) is caused by mutations leading to ectopic expression of the transcription factor DUX4, and encompasses both muscle-related and non-muscle phenotypes." (PMID 26978271, 2016). "The DUX4 gene, encoded within D4Z4 repeats on human chromosome 4q35, has recently emerged as a key factor in the pathogenic mechanisms underlying Facioscapulohumeral muscular dystrophy (FSHD)." (PMID 25742305, 2015). "Human DUX4 is kept silenced in differentiated tissues, as aberrant activation of DUX4 in muscle tissue upregulates HERVL, leading to unscheduled transcription activation of early embryonic genes which eventually resulted in facioscapulohumeral muscular dystrophy." (PMID 33727936, 2021). "We initially described iP300w as an effective inactivator of DUX4, a pioneer transcriptional factor that recruits P300/CBP through its C-terminal domain and plays a key role in early embryonic development and facioscapulohumeral muscular dystrophy (FSHD)." (PMID 39367409, 2024). "Pathogenesis in facioscapulohumeral muscular dystrophy (FSHD) is due to aberrant expression, particularly in skeletal muscle, of the 424 amino acid, full-length isoform of the double homeobox protein DUX4." (PMID 35191484, 2022). "The function of DUX family proteins is not known at present, but it has been reported that DUX4 may be involved in facioscapulohumeral muscular dystrophy (FSHD)." (PMID 26412852, 2015).
sarcoma (76 papers, 2017 to 2026). A usually aggressive malignant neoplasm of the soft tissue or bone. "Misexpression of DUX4 has been linked to several types of cancer, including sarcomas and leukemias, where it suppresses immune responses and contributes to tumor growth." (PMID 40427614, 2025). "DUX4’s misexpression is also linked to cancer, particularly sarcomas and B-cell leukemia, where it plays a role in cell proliferation, apoptosis, immune evasion, and transcriptional deregulation." (PMID 40427614, 2025). "DUX4 gene fusions have been identified as driver mutations in sarcomas, a rare group of malignancies that develop in connective tissue and bone." (PMID 40940582, 2025). "In cancers such as sarcoma and lymphoma, where DUX4 is re-expressed due to genetic rearrangements or mutations, ZSCAN4 expression results in telomere repair." (PMID 40427614, 2025). "In addition, analysis of CIC-DUX4 fusions in specific sarcomas show that fusion with the C-terminal 80 amino acids from 4q35-encoded DUX4-FL is sufficient to convert CIC into a transcriptional activator." (PMID 29618456, 2018). "Because CIC::DUX4 drives sarcoma development by activating a oncogenic transcriptional program, we performed a drug screen on human-derived CDS cell lines using a library of compounds that modulate transcription." (PMID 42302177, 2026). "While TF fusions represent cancer-specific alterations, the CIC::DUX4 fusion remains undruggable through direct pharmacologic targeting thus, effective therapeutic strategies to target CIC::DUX4 sarcomas remain elusive." (PMID 40760094, 2025). "The novel chromosomal translocation generating hybrid CIC–DUX4 proteins in Ewing-like sarcomas signalled a potentially wider role for DUX4 in pathology." (PMID 40855454, 2025). "To examine the potential role of POLE in inducing apoptosis in CIC::DUX4 sarcoma cells, we silenced POLE or CIC::DUX4 and measured Caspase 3/7 activity." (PMID 40760094, 2025). "Because CIC::DUX4 drives sarcoma development by activating a distinct oncogenic transcriptional program, we performed a drug screen on human-derived CDS cell lines using a library of compounds that modulate transcriptional regulation." (PMID 41279843, 2025). "The abnormal expression of DUX4 in cancers, particularly sarcomas and leukemias, results from both genetic alterations (such as translocations) and epigenetic reprogramming." (PMID 40427614, 2025). "Recently, we found that CIC::DUX4 sarcoma cells tolerate a high replicative stress state through an increased dependence on the G2/M checkpoint kinase, WEE1, which delays mitotic entry to enable DNA repair prior to mitosis." (PMID 40760094, 2025). "Recent molecular profiling has reclassified these tumors into distinct subtypes, including CIC::DUX4-rearranged sarcomas." (PMID 41053525, 2025). "Recent studies demonstrate that DUX4 expression in various cancers, including sarcoma and leukemia, induces a metastable early embryonic totipotent program." (PMID 40427614, 2025). "While multiple CIC gene fusions have been documented in the medical literature, the vast majority of CIC-rearranged sarcomas harbor the CIC::DUX4 gene fusion." (PMID 40599504, 2025). "There are several partner genes related to the CIC gene in CIC rearranged sarcoma, including DUX4, FOXO4, LEUTX, NUTM1, and NUTM2A, with the most common fusion type being CIC-DUX4." (PMID 40255429, 2025). "Since POLE expression associates with CIC-fusion expression and has an established role in DNA proofreading and replication, we aimed to investigate the role of POLE in the context of CIC::DUX4 sarcoma." (PMID 40760094, 2025). "To more broadly understand how POLE regulates cellular senescence in CIC::DUX4 sarcoma cells, we conducted transcriptional profiling (RNA-Seq) in POLE-deficient and POLE-replete NCC_CDS1_X1_C1 cells." (PMID 40760094, 2025).